TLR4 (toll like receptor 4)
Diseases named in the same sentence as TLR4 in open-access papers (continued):
Sharing a sentence is not in itself a finding about the gene and the disease.
Arthritis (continued). "Here we broaden our results, highlighting that during arthritis development, TLR4 dimerization in microglia within lipid rafts may contribute for arthritic pain processing too." (PMID 39696684, 2024). "Here, we show that in arthritis pain, dorsal horn microglia acquire a unique transcriptional profile that is driven by TLR4 upregulation and is enriched in pathways regulating the production and effect of IL-1β, TNF-α and IFN-β, which have been reported to regulate nociception in the K/BxN ST model." (PMID 37349313, 2023). "TLR4 has been shown to promote osteoclast-mediated bone erosion during arthritis through the detection of neutrophil-derived S100A8/A9, presenting the possibility that TLR4 plays a role in osteomyelitis, even in those cases triggered by Gram-positive pathogens." (PMID 36226943, 2022). "The TLR4 antagonist LPS-RS reversed mechanical hypersensitivity in a mouse model of arthritis pain." (PMID 35987639, 2022). "Specifically, in the spontaneous IL-1rn−/− mouse model of autoimmune arthritis, TLR4 signaling by the microbiome appears to be responsible for the induction of arthritis, as germ-free IL1rn−/− mice or conventional IL-1rn−/− TLR4−/− mice are protected from autoimmune arthritis." (PMID 33810172, 2021). "Furthermore, arthritis in these IL1rn−/− mice was diminished under germ-free conditions and was shown to be dependent on the activation of toll-like receptor 4 (TLR4) and subsequent enhanced Th17 differentiation." (PMID 34394100, 2021). "Furthermore, inhibition of B7-1 significantly enhances the MAM-initiated TLR4-dependent IL-17/Th17 cascade, thereby aggravating M. arthritidis-induced arthritis." (PMID 33704021, 2021). "In conclusion, TAP2 could effectively attenuate MIA-induced arthritis in rats by blocking TLR4 and its successive inflammatory cytokines and MMP13." (PMID 33060735, 2020). "To further determine that arthritis was caused by lupus serum but not LPS contamination, we used LPS‐resistant TLR4−/− mice and LPS‐responder control mice (TLR4+/+)." (PMID 32994999, 2020). "In addition, TLR4-dependent pathways have been shown to be involved in joint remodeling in arthritis mouse models." (PMID 31849953, 2019). "The TLR4 activation-induced or CXCR3-mediated CXCL10 upregulation can exert important roles in arthritis progression through TLR4 and CXCR3, suggesting that it could form a positive feedback loop between CXCL10 and its receptors TLR4 and/or CXCR3." (PMID 28724396, 2017). "Our observations suggest that TLR4-mediated modulation of the mucosal immune response in intestinal LP may be another function involving TLR4 in arthritis." (PMID 28645307, 2017). "However, recent studies reported that TLR4 KO mice exhibited either a similar progression of arthritis or a reduced arthritis even in the early induction phase compared to WT mice." (PMID 27313578, 2016). "Moreover, SLE patients carrying CD14*T/T/TLR4*A/A haplotype had significantly more arthritis (91.3%) than the rest of SLE group (73%), p = 0,044 and confirmed by multivariable analysis after adjustment according to age and gender, p = 0.01." (PMID 24252506, 2013). "As LPS is known as a specific ligand of TLR-4, interaction of IL-32α with TLR-4 may play a critical role in the development of arthritis, and this was also the case in LPS-triggered endotoxin shock in the Tg mice." (PMID 22613074, 2012). "Gr-1+ cell-depleted splenocytes partially restored arthritis in TLR4-/- mice." (PMID 23036692, 2012). "Therefore, macrophages, mast cells, Gr-1+ cells and invariant NKT cells promote antibody-induced arthritis by expressing TLR4." (PMID 23036692, 2012). "Adoptive transfer of WT, but not TLR4-deficient, iNKT cells promoted antibody-induced arthritis in CD1d−/− mice, suggesting that endogenous TLR4 ligands modulate iNKT cell function in arthritis." (PMID 23028952, 2012).
Arthritis (continued). "Indeed, IL-1RN KO mice housed in germ-free conditions display reduced arthritis assayed by ankle thickness and histopathological analysis, while arthritis can be induced by infection with Lactobacillus bifidus in a TLR4-dependent manner." (PMID 22229105, 2012). "Finally, TLR2−/− and TLR4−/− mice were found to have opposite phenotypes in a spontaneous model of murine arthritis." (PMID 21695198, 2011). "However, at day 90 after immunization, in the chronic stage of arthritis, the pro-inflammatory cytokines IL-12p70, TNF alpha and MCP-1 were suppressed in TLR4 deficient mice compared to wt mice." (PMID 21858160, 2011). "Also, it has been shown that the inhibition of TLR4 in different animal models of arthritis results in improved clinical manifestations and the prevention of the deleterious effects caused by inflammation in joints; this is by suppressing the production of pro-inflammatory cytokines." (PMID 39452128, 2024). "In addition, a recent study indicated that blocking TLR4 could effectively attenuate monoiodoacetate-induced arthritis in rats by relieving joint pain and reducing the expression of TNF-α, IL-1β, and matrix metallopeptidase-13 (MMP13)." (PMID 36785752, 2023). "We also provide evidence that TLR4 activation in immune cells contributes more strongly to pain in male mice, and may indicate that targeting this mechanism will be more effective for pain treatment in males with arthritis." (PMID 32796317, 2021). "In this study, we tested whether an antagonistic peptide of TLR4 could be an effective therapeutic for the pain and cartilage degradation of arthritis because TLR4-mediated inflammation contributes to the induction of cartilage damage and propagation of arthritic pain." (PMID 33060735, 2020). "In addition, previous results suggest that TLR4 may be involved in arthritis-dependent joint destruction." (PMID 31849953, 2019). "Moreover, a TGF-β blockade restored arthritis in TLR4-/- mice." (PMID 23036692, 2012). "Another member of the tenascin family, Tenascin C (Tnc), was recently shown to be an endogenous activator of TLR4, an inducer of IL-6 and TNFα, and was required for joint damage in arthritic mice, suggesting that Tnn could have a function similar to Tnc in arthritis." (PMID 23249408, 2012). "However, WT and IL-17-/- mice showed similar joint inflammation and cytokine production in the K/BxN serum transfer model, suggesting that IL-17 may have minimal involvement in the TLR4-mediated regulation of antibody-induced arthritis." (PMID 23036692, 2012). "To determine whether joint immune cells produce IL-12 via TLR4 signals during arthritis, we performed intracellular staining for IL-12p35 in joint macrophages and mast cells from WT mice with antibody-induced arthritis, some of which had been injected with LPS." (PMID 23036692, 2012). "Lactobacillus bifidum exacerbated arthritis by promoting Th17 and Th1 responses via TLR2/TLR4 signaling." (PMID 41019075, 2025). "In collagen-induced arthritis and collagen antibody-induced arthritis mouse models, ferroptotic M2 macrophages released HMGB1, which engaged TLR4 and activated STAT3 signaling in M1 macrophages, fueling inflammatory amplification loops." (PMID 40722994, 2025). "Meanwhile, evidence from animal models suggested that EA can also alleviate arthritis by inhibiting TLR2 and/or TLR4 signaling." (PMID 36785752, 2023). "Another study demonstrated the involvement of the Toll-like receptor 4 pathway and the beneficial use of the TNF-α antagonist infliximab for the treatment of joint inflammation in MPS VI." (PMID 36556450, 2022). "TLR4 expression of human OA chondrocytes and synoviocytes and the knee joint tissue of MIA-induced arthritis were evaluated." (PMID 33060735, 2020). "Therefore, TLR4 could be a plausible target for the progression of arthritis induced by MIA." (PMID 33060735, 2020).
Arthritis (continued). "For therapeutic purposes, it would be beneficial to inhibit TLR4 signals, IL-12 production, and the effects of IL-12 on IL-1β and IFN-γ production in antibody-induced joint inflammation." (PMID 23036692, 2012). "Recombinant IL-12, IFN-γ and IL-1β administration restored arthritis, but reduced joint TGF-β levels in TLR4-/- mice." (PMID 23036692, 2012). "In skg mice, the development of arthritis is Dectin- dependent, while in the IL-1ra −/− model, disease is critically dependent on TLR-function, namely TLR4." (PMID 21858160, 2011). "Complementary studies using A20myel-KOIl1rKO double-knockout mice reveal near-complete disease resolution, confirming the non-redundant roles of both TLR4 and IL-1R signaling pathways in arthritis pathogenesis." (PMID 41583484, 2025). "Notably, tenascin-C, an endogenous ligand for TLR4, is upregulated in glaucomatous ONH and has been shown to activate TLR4 signaling in arthritis." (PMID 41409280, 2025). "Despite the consistent success of selective inhibition of TLR ligation in animal models, DV-1179 (dual TLR7/9 antagonist) failed to achieve pharmacodynamic effectiveness in SLE, and NI-0101 (mAb against TLR4) failed to improve arthritis in RA." (PMID 38255243, 2024). "Wherein, the optimal AnCar‐ExoLaIMTS3 can efficiently deliver therapeutic contents to pro‐inflammatory macrophages mainly through TLR4‐mediated endocytosis, which ameliorates the severity of arthritis without obvious toxicity." (PMID 38083984, 2024). "A penetration-conjugated small peptide (TIP3) could block cytokine production to ameliorate inflammatory response in mice models of arthritis and alleviate the disease symptoms of SLE models through the TLR4 pathway." (PMID 37771504, 2023). "The fact that TLR4 and TLR1 may be involved in the pathogenesis not only of RA but also of other forms of arthritis, including OA, is also indicated by the correlation analysis between clinical parameters and TLR gene expression." (PMID 35126351, 2021). "In the present study, a statistically significant negative correlation was determined between anti-CCP and TLR4 expression levels, potentially due to a separation of patients with early or long arthritis duration." (PMID 35126351, 2021). "In contrast to PIA, the acute phase of SCW‐induced arthritis is TLR2 dependent but shifts towards a TLR4 dependency in the chronic phase, in which TLR2 is no longer relevant." (PMID 29992753, 2018). "Furthermore, mono-colonisation with Lactobacillus bifidus was shown to be sufficient for inducing joint inflammation in a mouse model of spontaneous arthritis via TLR2- and TLR4-dependent signalling affecting the balance between Treg, Th17 and Th1 in the gut." (PMID 26822477, 2016). "It was shown that arthritis progression in TLR4 KO mice had a similar initiation phase but was not sustained compared to WT mice, suggesting that TLR4 plays a role in the later phase in the model." (PMID 27313578, 2016). "MRP8/14 is a ligand to toll-like receptor 4 (TLR-4), has a pro-inflammatory effect on phagocytes and endothelial cells and is an important factor in mediating osteoclastic bone destruction in experimental arthritis." (PMID 26249667, 2015). "Taken together, these results suggest that TLR4-mediated IL-12 production by macrophages, mast cells and Gr-1+ cells enhances joint production of IFN-γ and IL-1β, which suppresses TGF-β production, and thereby promotes antibody-induced arthritis." (PMID 23036692, 2012). "Injection of LPS into WT mice exacerbated joint swelling during antibody-induced arthritis, but it did not alter joint inflammation in TLR4-/- mice." (PMID 23036692, 2012). "Consistent with the results of our in vitro experiments, recombinant IL-12 increased the expression of IFN-γ and IL-1β in the joints of TLR4-/- mice with arthritis, whereas neither recombinant IL-1β nor IFN-γ altered joint IL-12p35 expression levels." (PMID 23036692, 2012).
Arthritis (continued). "TLR4-mediated IL-12 production by joint macrophages, mast cells and Gr-1+ cells enhances IFN-γ and IL-1β production, which suppresses TGF-β production, thereby promoting antibody-induced arthritis." (PMID 23036692, 2012). "Injection of lipopolysaccharide (LPS) enhanced arthritis and exaggerated joint cytokine alterations in WT, but not TLR4-/- or IL-12p35-/- mice." (PMID 23036692, 2012). "Despite the evidence from preclinical mechanistic studies and human genetics about the potential involvement of TLR4 in the perpetuation of RA synovitis, NI-0101, a humanized mAb against TLR4, failed to improve arthritis in RA patients with an inadequate response to methotrexate." (PMID 38255243, 2024). "Likewise, TLR-4 mRNA expression in the ileum of AIA was not different from controls whatever the stage of arthritis." (PMID 37280714, 2023). "Further, arthritis was not sustained in toll-like receptor 4 (TLR4) mutant mice." (PMID 22551352, 2012). "To investigate LPS-mediated TLR4 signaling in antibody-induced arthritis, we injected WT mice with an amount of K/BxN serum that resulted in sub-maximal joint swelling because LPS injection did not alter full-blown arthritis in WT mice." (PMID 23036692, 2012). "Western blotting revealed that recombinant IL-12 increased pro-IL-1β expression in joint cells from WT mice with arthritis in the presence or absence of LPS, suggesting that TLR4-mediated IL-12 regulates the production of pro-IL-1β in joint cells, rather than its cleavage." (PMID 23036692, 2012). "Moreover, TLR4-mediated differential cytokine production by iNKT cells modulates immune responses in various iNKT cell-mediated immune diseases such as SR-induced HP, BIPF, and antibody-induced joint inflammation in mice." (PMID 23028952, 2012). "In the absence of functional TLR4 the clinical severity of arthritis was lowered." (PMID 21858160, 2011). "In addition, the knockout of TLR9 resulted in no progression of arthritis, suggesting that these three TLRs (i.e., TLR2, TLR4, and TLR9) have different relationships with the induction of arthritis and IL-17 production." (PMID 30103522, 2018). "Experimental studies utilizing A20myel-KO mice reveal that neither NF-κB inhibition via IKK2 deletion nor TNFR1 ablation fully prevents arthritis, suggesting redundant inflammatory pathways, such as TLR3/TLR4-TRIF or IFN receptor signaling, may compensate to sustain disease progression." (PMID 41583484, 2025).
ulcerative colitis (113 papers, 2009 to 2026). An inflammatory bowel disease involving the mucosal surface of the large intestine and rectum. "Dysregulation of mTOR phosphorylation and autophagy-related proteins has been identified in inflamed colonic tissues from patients with active ulcerative colitis and is associated with TLR4-MyD88 signaling." (PMID 39770669, 2024). "TLR4 is notably upregulated in the intestine under inflammatory states including in people with ulcerative colitis, and this is further linked to ulcerative colitis-associated CRC risk and development." (PMID 35841426, 2023). "Two such SNPs on TLR4 associated with ulcerative colitis are D299G and T399I that prevent the interaction of TLR-4 with the TLR adaptor molecules MYD88 and TRIF36,37." (PMID 34724858, 2021). "TLR4 signaling in intestinal epithelial cells in turn is a key component of homeostasis and activation of the TLR4 pathway and has been associated with both Ulcerative colitis and Crohn’s disease." (PMID 29352257, 2018). "The anti-inflammation effect of baicalin on ulcerative colitis was associated with the inhibition of TLR4/NF-κB signaling pathway." (PMID 27855209, 2016). "TLR4 interacts with ligands such as heat-shock proteins; TLR4 polymorphisms reportedly link with inflammatory disease and/or cancer: e.g., Crohn’s disease, ulcerative colitis, cervical cancer." (PMID 25520922, 2014). "Meanwhile, Cur supramolecular nanoparticles inhibit inflammation via the TLR4/NF-κB signaling pathway, mitigate oxidative damage by influencing Nrf2/HO-1 signaling, promote macrophage reprogramming, and accelerate the repair caused by ulcerative colitis." (PMID 41169791, 2025). "TLR3 signaling is associated with antiviral immune responses as well with the pathogenesis of inflammatory disease, and TLR4 is shown to be upregulated during inflammation and two single nucleotide polymorphisms in the TLR4 gene are associated with Ulcerative colitis and Crohn’s disease." (PMID 35011620, 2021). "In this study, we aimed to determine whether TLR4 gene was associated with Crohn’s disease (CD) and ulcerative colitis (UC) among Moroccan patients, and evaluated its correlation with clinical manifestation of the disease." (PMID 25492126, 2014). "Colon-targeted microgels alleviate ulcerative colitis by suppressing the TLR4/MyD88/NF-κB inflammatory axis and restoring gut microbiota homeostasis." (PMID 42126727, 2026). "Recent studies have demonstrated that QA improves ulcerative colitis in rats by inhibiting TLR4/NF-κB and NF-κB/iNOS/NO signaling pathways." (PMID 40538727, 2025). "Lipopolysaccharide-binding proteins, Toll-like receptor 4, and bacterial permeability-increasing proteins have been detected in the serum of patients with ulcerative colitis, and these complexes are recognized by CD14." (PMID 39995691, 2025). "Our results explore the treatment effect of CPH on ulcerative colitis via dephosphorylation of NF‐κB, TLR4, and MyD88, respectively, in CPH treatment groups." (PMID 39723032, 2024). "Some studies have confirmed that TLR4 expression was significantly increased under various stimuli, such as ulcerative colitis." (PMID 39139212, 2024). "Patients with active ulcerative colitis often exhibit high levels of TLR4 expression in the intestinal epithelium, indicating the potential involvement of TLR4 in the progression of UC." (PMID 38516705, 2024). "Our research team found that EMO can exert anti-inflammatory effects through modulation of the Toll-like receptor 4/nuclear factor kappa-B (TLR4/NF-κB) signaling pathway for the treatment of ulcerative colitis." (PMID 38238760, 2024). "In a previous study, obacunone attenuated ulcerative colitis symptoms in mice by modulating the gut microbiota, disrupting the TLR4/NF-κB signaling cascades, and restoring intestinal epithelial barrier integrity." (PMID 38357365, 2023).